IL17A (interleukin 17A)
Diseases named in the same sentence as IL17A in open-access papers (continued):
Sharing a sentence is not in itself a finding about the gene and the disease.
tumor (continued). "In immunotherapy studies for rectal colon cancer, IL-17A was shown to increase PD-L1 expression via the p65/Nrf2/miR-15b-5p axis, helping tumor cells to undergo immune escape, and blocking IL-17A improved the efficacy of anti-PD-L1." (PMID 37978543, 2023). "A similar trend was observed in the relative frequencies of IFNγ+ CD4+ to IL-17A+ CD4+ T cells (Tumor 9.7% versus 5.5%; STM 8.2% versus 1.3%)." (PMID 38074634, 2023). "Observing the serum IL-17A concentration after surgery during adjuvant treatment, a significant positive correlation was found with histological grade, nuclear grade, tumor size and lymph node involvement." (PMID 37427128, 2023). "We further analyzed the expression of IL-17A and PD-L1 in NSCLC tumor tissues, and found that the IL-17A positive rate reached 87.2%." (PMID 37978543, 2023). "Within the lung microenvironment, γδ T cells are activated to produce IL-17A by tumor-derived or microbiota-induced IL-1β and IL-23, two cytokines with well-established influence on IL-17A–producing γδ T cells." (PMID 36480166, 2023). "We quantified the expression of IL-17A in tumor tissues using mean density values, and divided NSCLC patients into IL-17A low and high expression groups by the median of their expression level, and negative cases were classified as low expression group." (PMID 37978543, 2023). "At the cellular level, IL-1β is known to stimulate angiogenesis in the tumor microenvironment (TME), and to induce the production of IL-6 and IL-17A, which are well-established mediators of tumor growth." (PMID 36670473, 2023). "Studies using chemically induced skin carcinogenesis have pinpointed a requirement for IL-17A signaling in cancer cells to drive tumor growth." (PMID 36696569, 2023). "IL-17A is reported to be involved in tumor cell migration and invasion, chemotherapy resistance, and immunosuppression, promoting cancer progression and metastasis." (PMID 36125689, 2023). "Meanwhile, a significantly positive correlation was found between the peristromal IL-17A expression and tumor nuclear grade, proliferation index Ki-67 and the use of chemotherapy, while a negative correlation was observed with age and menopause." (PMID 37427128, 2023). "We found a prevalent expression of IL-17A in NSCLC tumor tissues and it was positively correlated with PD-L1 expression (r = 0.6121, p < 0.0001)." (PMID 37978543, 2023). "While Th17 and Th22 cells directly promote tumor progression through the release of tumor-promoting cytokines such as IL-17A or IL-17, Tregs suppress the anti-tumor effector response of Th1 cells and cytotoxic CD8 T cells." (PMID 37190048, 2023). "Driven by BTNL2, γδT17 cells secrete IL-17A and recruit myeloid suppressor cells, resulting in an increase in the number of TME mesenchymal stem cells, M2 macrophages and tumor-associated macrophages (TAMs)." (PMID 36793048, 2023). "To confirm the consistency of the effects of IL-17A in vitro and in vivo, we examined the expression of p62 and Nrf2 in tumor tissues, which were decreased." (PMID 37978543, 2023). "In our research, the serum IL-17A level significantly negatively correlated with the tumor ER expression before surgery, but also during adjuvant treatment." (PMID 37427128, 2023). "The ratio of TNFα+ CD4+ and IL-17A+ CD4+ was also skewed towards more IL17A+ CD4+ in tumor compared with STM." (PMID 38074634, 2023). "Downregulated NF-κB further contributes to reduce the secretion of IL-6, TGF-β1, VEGF, and IL-17A in tumor cell and increase the level of regulatory T cells that collectively inhibits the progression of epithelial ovarian cancer." (PMID 37822929, 2023). "In this study, we uncovered a novel role of abnormally generated IL-17A on tumor infiltration of two exhausted CTL subsets." (PMID 37605139, 2023). "IL-17A plays a key role in fostering the creation of an ideal tumour microenvironment through its ability to induce the production of inflammatory mediators and mobilize MDSC cells." (PMID 37483633, 2023).
tumor (continued). "IL-17A-induced Lrig1+ cell expansion was reduced, and oncogenic K-Ras G12D-mediated activation of tumor formation was inhibited." (PMID 37816755, 2023). "Upregulation of IL-17A is observed in serum and tumor samples of GC patients compared to healthy controls." (PMID 36125689, 2023). "Th17 cells and their cytokine IL-17A have been proven to promote the proliferation and invasion ability of tumor cells in cancer immunity, thus inducing cancer recurrence and metastasis." (PMID 37330523, 2023). "A comparative analysis revealed a notable shift in the ratio of IFNγ+ CD8+ to IL-17A+ CD8+ T cell frequencies (Tumor- 31.2% versus 1.4%; STM- 17.3% versus 0.4%)." (PMID 38074634, 2023). "The results demonstrated that the survival rate of tumor cells was markedly improved with high IL-17A expression." (PMID 37978543, 2023). "Inhibited tumor growth.Enhanced tumor immune response.Increased the number of tumor-infiltrating M1 macrophages and dendritic cells.Enhanced the secretion of IL17A in spleen.Increased the level of TNF-α in tumor." (PMID 37242947, 2023). "Abt mice also showed increased sensitivity to tumor development, accompanied by decreased expression of IL-17A, IL-6 and IL-23 by γδT17 cells and partially inhibited function of CD8+ αβT cells." (PMID 36793048, 2023). "Mast cells can promote tumor proliferation through direct contact with tumor cells or the secretion of factors such as IL-17A." (PMID 37178254, 2023). "The correlation of serum IL-17A concentration and different clinical and pathological parameters, including IL-17A expression in the corresponding tumor tissue samples, was analyzed." (PMID 37427128, 2023). "Neutralizing IL-17A improved tumor infiltration of “stem-like exhausted” CTLs and enhanced the anti-PD-1-mediated antitumor efficacy." (PMID 37605139, 2023). "Our findings suggest that IL-17A promotes tumor progression through regulating stemness of GC cells." (PMID 36125689, 2023). "Meanwhile, tumor cells with high IL-17A expression can reduce cellular PD-L1 degradation by blocking autophagy, contributing to sustained high PD-L1 expression in tumor cells." (PMID 37978543, 2023). "In the study, overexpression of IL-17A cytokine in the pancreas significantly accelerated PanIN initiation and progression in mouse models, suggesting a tumor-promoting role for IL-17 signaling albeit the molecular mechanisms required further investigation." (PMID 37771596, 2023). "Mechanistically, tumor-infiltrating IL-1β activated IL-17A+ γδ T cells, enhancing the priming and recruitment of IFN-γ-producing CD8+ T cells that exert antitumor effects." (PMID 37631976, 2023). "Collectively, our finding revealed that C. albicans promoted OC development via the IL-17A/IL-17RA-macrophage axis, opening perspectives for revealing C. albicans-tumor immune microenvironment links." (PMID 37067414, 2023). "The concentration of IL-17A in serum during adjuvant therapy was also significantly positively correlated with the histological grade, nuclear grade, tumor size and the involvement of axillary lymph nodes." (PMID 37427128, 2023). "Further assessment of frequencies and relative levels of other effector T cell populations in tumor versus STM showed a notable shift in the ratio of IFNγ+ to IL-17A+ T cell frequencies (on both CD4+ and CD8+ T cell subsets)." (PMID 38074634, 2023). "It is reported that the IL-17A signaling pathway can enhance the immunosuppressive activity of regulatory T cells (Tregs), leading to tumor growth and development." (PMID 38022654, 2023). "We validated the upregulation of Il17a, Il17f, Havcr2, and Areg at protein level in Vγ4+ and Vγ6+ cells from the lungs of WT and tumor-bearing KB1P mice by flow cytometry." (PMID 36480166, 2023). "Subcutaneous tumor models were established to examine the tumor-promoting effect of IL-17A in vivo and its effect on immunotherapy." (PMID 37978543, 2023).
tumor (continued). "Our current study indicated that IL-17A stimulation mainly suppressed the tumor infiltration of stem-like CTLs." (PMID 37605139, 2023). "The results showed that both IL-17A neutralization and macrophage depletion tended to reduce the TAMs number and tumor size in mice with C. albicans infection." (PMID 37067414, 2023). "Adoptive transfer of HDAC-6-deficient Th17 cells can increase IL-17A in the HCC TME, thereby enhancing the anti-tumor response mediated by CD8+ T cells." (PMID 37304265, 2023). "A total of 96 genes, including Il17a, were upregulated in cells from tumor-bearing KB1P mice when compared with cells from WT mice, while 72 genes were downregulated." (PMID 36480166, 2023). "Given the higher promoter activity of the IL17A gene in the presence of the variant allele, we could assume that the A/A-genotype contributes to the maintenance of inflammation and stimulation of angiogenesis in the growing tumor, which would lead to earlier CRC onset." (PMID 36422171, 2022). "The 10-fold upregulation of IL17A alludes to the role of IL-17-producing CD4+ T cells (Th17 cells) during tumor development, which drive tumorigenesis." (PMID 35356003, 2022). "The correlation between IL17A expression and immune cell marker indicated a key role for IL17A in regulating tumor immunology in HNSCC." (PMID 35902909, 2022). "In advanced‐stage CRC, Th17 inhibits migration of CTLs in tumor tissues by downregulating the expression of CXCR3 via the IL‐17A/STAT3 axis." (PMID 35791509, 2022). "We investigated the correlation between IL17A expression and certain clinical parameters, tumor-infiltrating immune cells (TIICs) in TCGA HNSCC samples." (PMID 35902909, 2022). "Previous studies have shown that IL-17A can promote tumor immunosuppression and induce immune escape in colorectal cancer." (PMID 35665407, 2022). "The induced Th17 (iTh17) cells from young mice splenocytes treated with PRI-2191 expressed significantly higher levels of Il17a mRNA as compared to iTh17 splenocytes obtained from control tumor-bearing mice." (PMID 35954312, 2022). "We believed that IL-17A level in tumor specimens is more realistic to reflect the infiltration of inflammation in tumor sites, which is beneficial to identify the correlation between the microenvironment of NSCLC and inflammatory response." (PMID 35665407, 2022). "In contrast, IL-5, IL-17A, IL-21, IL-22, and TGFβ concentrations in the tumour tissue of IL-9 knockout mice were significantly reduced compared with wild-type mice, indicating that IL-9 controls the production of Th2- and Th17-associated cytokines." (PMID 35793807, 2022). "In contrast, IL-17A can promote tumor development by promoting angiogenesis of endothelial cells and fibroblasts." (PMID 35665407, 2022). "In the current study, we found that BTNL2 blockade reduced MDSC infiltration of the TME, which we found was primarily mediated by IL-17A production by tumour-infiltrating γδ T cells." (PMID 35017553, 2022). "In the 4T1 mouse model (young mice), in which calcitriol and its analog increased the IL-17A secretion of iTh17 cells, increased blood perfusion within the tumor was observed." (PMID 35954312, 2022). "IL17a is widely found in the inflammatory microenvironment of various tumors and is involved in tumor cell dissemination, chemotherapy resistance, and immunosuppression." (PMID 35504900, 2022). "IL-17A participates in tumor angiogenesis by binding to its receptor on vascular endothelium, promoting angiogenesis and inflammatory response, possibly engaging the IL-17-STEAP4-XIAP pathway and contributing to the immortalization of cancer cells." (PMID 35884974, 2022). "This strongly indicates that the anti-tumor activity of IL-17A in CRC is mediated by DCs expressing TNFS11 and the CCR6-CCL20 chemotactic axis, which induce the engagement of the CD8+ T cells." (PMID 36098359, 2022).
tumor (continued). "In conclusion, the present study revealed that the Th1/Th17 cell subsets in the CIK cell population can effectively improve the function of T cells and recruit T-cell infiltration into tumor tissues by releasing IL-17A and IFN-γ." (PMID 35523765, 2022). "Interleukin-17A is induced during colorectal tumorigenesis and angiogenesis, although some studies have reported an anti-tumor effect as well." (PMID 36098359, 2022). "IL-17A mainly comes from Th17 cells and is related to tumor occurrence, proliferation, and angiogenesis." (PMID 36185234, 2022). "R (Version 3.6.3) software, GEPIA, and TIMER online analysis tools were used to profile the relationship between the expression of IL17A and the prognosis, clinical stages, survival status and immune cell tumor-infiltrating levels of HNSCC patients." (PMID 35902909, 2022). "At present, however, the roles of IL-17A and Th17 cell subsets in the tumor microenvironment are controversial." (PMID 35523765, 2022). "In particular, as a bridge of innate and adaptive immunity, Th cells and interleukin-17A (IL-17A) cytokine secreted after stimulation become a new focus of tumour immunity." (PMID 36349316, 2022). "Mechanistically, BTNL2 interacts with local γδ T cell populations to promote IL-17A production in the tumour microenvironment." (PMID 35017553, 2022). "Second, IL‐17A and G‐CSF with pro‐inflammatory feature are produced by Th17 cells and tumor cells within GC environment." (PMID 34957697, 2022). "In this study, we provide evidence that BTNL2 inhibits anti-tumour immunity by acting on local γδ T cell populations to promote IL-17A production, which enhances tumour immune resistance via recruitment of MDSCs." (PMID 35017553, 2022). "Surprisingly, EVax‐mediated tumor growth inhibition was further increased in mice treated with anti‐IL‐17a." (PMID 35861366, 2022). "IL-17a is a critical proinflammatory and tumor promoting cytokine that regulates de novo lipogenesis and chemokine production in metabolically injured hepatocytes." (PMID 35756539, 2022). "Patients with tumor progression and resistance to treatment presented then with an increasing plasma rate of IL17A and TNF after the first infusion of pembrolizumab, in comparison to patients with DCB." (PMID 35794623, 2022). "More importantly, AOM/DSS T cells highly expressed Id2 downstream of TGFβ signaling, which has been shown to lead to RORα-dependent tumor-promoting inflammation, evident in this population by high Rora and Il17a expression." (PMID 35600339, 2022). "Il17a and Il6, both of which possess a dichotomic role in tumor immunity were also increased, further indicating that NK cells bolstered the anti-tumor function of m-reMAIT cells." (PMID 36551916, 2022). "Consistent with our prior findings, these data further confirmed that Vγ1 γδ T cells were the major IL-17A-producing γδ T cells in tumours, and the anti-tumour effect of BTNL2 blockade was dependent on the regulation of Vγ1 γδT17 cells." (PMID 35017553, 2022). "Although inhibiting IL‐17A reduces intestinal inflammation to some extent, inhibiting IL‐22 markedly reduces dysplasia and tumor burden in a mouse model of CRC." (PMID 35791509, 2022). "In the present study, we integrated IL17A expression and prognostic values in HNSCC using TCGA, GEPIA, TIMER databases and R. IL17A expression was decreased in tumor tissues compared with that in paired normal samples." (PMID 35902909, 2022). "Th17 cell‐derived IL‐17A and tumor cell‐derived G‐CSF activate ERK‐NF‐κB and JAK‐STAT3 signaling pathways to induce FasL and PD‐L2 expression on neutrophils." (PMID 34957697, 2022). "Th17 cells, have also a dual effect, since IL17A/F can promote angiogenesis in a direct (on tumour cells) or indirect (on stromal cells of the TME) manner." (PMID 35406451, 2022).
tumor (continued). "Note that the basal tumorigenic activity of SW480-FR-CICs was much higher compared to SW480-S-CICs, and treatment with each of the three stromal-secreted factors (PN, WNT3A and IL17A) increased tumor sphere formation ability relative to vehicle treated CICs." (PMID 35982950, 2022). "Overall, the data presented herein strongly supports the contribution of IL-17A produced from γδ T cells for modulating a tumor microenvironment with increased T cell infiltration and cytotoxic activity upon exposure to DOX in TNBC." (PMID 35924165, 2022). "Several previous reports have suggested that Vγ4 and Vγ6 γδ T cells are the major IL-17A-producing γδ T cell subsets in mouse tumour models." (PMID 35017553, 2022). "In TNBC tumors sensitive to DOX, increased IL-17A levels lead to a direct effect on cancer cell responsiveness and chronic stimulation of tumor infiltrated T cells leading to improved chemotherapeutic efficacy." (PMID 35924165, 2022). "It has been reported that IL-17A exhibits antitumor effects during tumor occurrence and metastasis, acting as a prognostic biomarker." (PMID 35459193, 2022). "Mechanistically, Th17 cell‐derived IL‐17A and tumor cell‐derived G‐CSF can significantly induce neutrophil FasL and PD‐L2 expression via activating ERK‐NF‐κB and JAK‐STAT3 signaling pathway, respectively." (PMID 34957697, 2022). "Estrogen also appears to weigh the tumour immune balance towards tumour-promoting cytokines (IL-6, IL-4, TNF and IL-17A), M2 (pro-tumour) macrophage polarisation and diminished functional capacities of anti-tumour NK and CD8+ T cells." (PMID 36347875, 2022). "In vitro analysis of IL-17’s activity directly on cancer cells showed anti-tumor effects by increasing tumor responsiveness to DOX upon co-administration with recombinant IL-17A." (PMID 35924165, 2022). "The mast cells-derived IL-17a also contributes to the tumor fibrosis in peritoneal dissemination in GC." (PMID 35311157, 2022). "Analysis of effector cytokines Ifng, Il9, Il17a and Il4 mRNA in tumor-infiltrating immune cells revealed that Ifng and Il9, but not Il17a or Il4, expression was increased following cGAMP administration." (PMID 35091453, 2022). "Protein quantification by western blot further confirmed 257% higher IL-17A levels in homogenized tumor samples of sensitive tumors compared to resistant tumors." (PMID 35924165, 2022). "Th17 cells can secrete the cytokines IL-17A, IL-17F, IL-22, and TNF-α and can mobilize and activate neutrophils through secreted IL-17 A/F, and these cells thereby induce autoimmune responses, tumor inflammatory responses, or transplant immune rejection." (PMID 36225183, 2022). "IL-17A is a proinflammatory cytokine, known for its function in regulating tumor progression in CRC." (PMID 37529004, 2022). "Here authors show that BTNL2 expression on cancer cells generates a dysfunctional tumour immune microenvironment via promoting IL-17A-producing γδ T cells." (PMID 35017553, 2022). "In conclusion, high levels of IL-17A mRNA in the CRC tissues were associated with better survival and early tumor stage and likely indicate a favorable prognosis." (PMID 36098359, 2022). "Ten datasets included the expression data of TNFSF11 and CCR6-CCL20 mRNAs, which mediate the anti-tumor effects of IL-17A." (PMID 36098359, 2022). "Some studies have shown that IL-17A contributes to reducing tumour growth and metastasis and improves prognosis." (PMID 36349316, 2022). "This study showed that TANs promote tumor EMT by the secreted IL17a via the JAK2-STAT3 signaling pathway." (PMID 36211375, 2022). "Next, we assessed differences of the 24 immune infiltrated cell subtypes levels in tumor between high and low IL17A expression groups." (PMID 35902909, 2022). "IL-17A, an inflammatory mediator mainly secreted by Th17 cells, has been shown to promote tumor development and play a strong proinflammatory role in immune diseases." (PMID 35991881, 2022).